MTOR (mechanistic target of rapamycin kinase)
Diseases named in the same sentence as MTOR in open-access papers (continued):
Sharing a sentence is not in itself a finding about the gene and the disease.
retinoblastoma (30 papers, 2010 to 2025). A malignant tumor that originates in the nuclear layer of the retina. "The mTOR pathway is one of the most commonly deregulated pathways in cancer and has been implicated in the tumorigenesis of retinoblastoma." (PMID 29179444, 2017). "We next determined if co-inhibiting the PI3K and mTOR pathways caused apoptosis of tumor cells in our retinoblastoma mouse model." (PMID 28445155, 2017). "In retinoblastoma cell lines, METTL3 was higher than that in normal ARPE-19 cells, and upregulation of METTL3 promoted the growth of retinoblastoma via the PI3K/AKT/mTOR signaling pathway." (PMID 36830067, 2023). "In conclusion, osthole exerts an anti-retinoblastoma effect by regulating the circ_0007534/miR-214-3p axis and inhibiting the PI3K/AKT/mTOR pathway, which provides a novel approach for the diagnosis and treatment of retinoblastoma based on biological markers." (PMID 36505874, 2022). "Among them, miR-218-5p is a tumor suppressor miRNA, which can inhibit the progression of retinoblastoma by targeting NACC1 to inhibit AKT/mTOR signaling pathway." (PMID 35465266, 2022). "It has been revealed that the PI3K/AKT/mTOR pathway plays an important role in the development of the retinoblastoma." (PMID 34840573, 2021). "Isoflavones also inhibited human retinoblastoma growth in vivo; western blot analysis showed inhibition of mTOR and downregulation of cyclin E1 in an isoflavone-treated xenograft mouse model." (PMID 29179444, 2017). "We do not observe strong activation of the ribosomal S6 protein, which is downstream of mTOR, in retinoblastoma." (PMID 28445155, 2017). "Inhibition of the mTOR pathway can block the cell cycle between G0 and G1; this is indicated by a marked decrease in G1 cyclins in retinoblastoma cells." (PMID 29179444, 2017). "Together, these results illustrate that isoflavones inhibit retinoblastoma tumour growth in vitro and vivo and that inactivation of the mTOR pathway and downregulation of cyclin E1 is involved in this action." (PMID 29179444, 2017). "The second was to utilize our mouse retinoblastoma model as a pre-clinical model to test the efficacy of PI3K/mTOR inhibition, alone or in combination therapy with chemotherapeutic agents." (PMID 28445155, 2017). "We therefore investigated the phosphorylation of mTOR in human retinoblastoma Y79 cells after treatment with isoflavones with western blot analysis." (PMID 29179444, 2017). "In the present study, inhibition of mTOR and downregulation of cyclin E1 occurred in isoflavone-treated human retinoblastoma Y79 cells and in an isoflavone-treated xenograft mouse model." (PMID 29179444, 2017). "This was supported by in vitro and in vivo data showing that isoflavones decreased mTOR phosphorylation, with a concomitant decrease in cyclin E1, which inhibited G1/S progression of human retinoblastoma Y79 cells." (PMID 29179444, 2017). "In our in vivo study, we showed that AICAR treatment induced the activation of AMPK, and inhibited mTOR signaling indicated by dephosphorylation of pS6RP (Ser235/236) and p4EBP-1 (Ser65) in retinoblastoma tumor xenografts." (PMID 23300996, 2013). "We have recently demonstrated that AICAR was an efficient inhibitor of retinoblastoma cell proliferation in vitro through S-phase arrest, decrease of cyclins A and E, and partial inhibition of the mTOR pathway." (PMID 23300996, 2013). "Furthermore, METTL3 promotes the proliferation of retinoblastoma cells by activating PI3K–Akt–mTOR signaling pathways." (PMID 37858219, 2023). "Overexpression of mTOR in non-transformed wt fibroblasts promoted AR, and mTOR knockdown in MEFs deficient in all retinoblastoma-family members restored anoikis." (PMID 37081871, 2023). "Hence, the identification of PI3K as hub gene in Rb tumors is evidential of the role of PI3K/Akt/mTOR signaling pathway in Rb tumor progression." (PMID 35359459, 2022).
retinoblastoma (continued). "In summary, the results of this study suggested that isoflavones reduced cell viability and triggered G1-phase blockage by down regulating cyclin E1 protein in human retinoblastoma Y79 cells in vitro and in vivo, mediated through the inhibition of the mTOR pathway." (PMID 29179444, 2017). "The mTOR pathway is commonly deregulated in human malignancies, including retinoblastoma." (PMID 29179444, 2017). "Thus we next examined the effects of AICAR on the activity of the mTOR pathway by Western blot analysis of retinoblastoma xenografts extracts." (PMID 23300996, 2013). "Our previous study showed that AICAR inhibits the growth of human retinoblastoma cells in vitro through inhibition of the mTOR pathway, down-regulation of cyclins A and E, and through inhibition of p21, which in retinoblastoma cells may act as an oncogene." (PMID 23300996, 2013). "Moreover, several studies have demonstrated the negative effects of inhibiting autophagy on CSCs renewal and proliferation, but it was found that in retinoblastoma, lupeol promoted autophagy through the PI3K/AKT/mTOR pathway in retinoblastoma and reduced the number of retinoblast stem cells." (PMID 37422448, 2023). "For example, MEG3 is downregulated in both retinoblastoma and BC cells, and its overexpression suppresses proliferation while inactivating the PI3K/Akt/mTOR pathway, thereby reducing migration and enhancing apoptosis." (PMID 40350996, 2025). "In retinoblastoma, the m6A methyltransferase METTL3 promotes retinoblastoma progression through the PI3K/AKT/mTOR pathway." (PMID 35945641, 2022). "In retinoblastoma cells, lncRNA‐H19 knockdown suppressed cell viability, migration, and invasion together with inhibition of PI3K/AKT/mTOR pathways." (PMID 33107222, 2021). "Treatment with BEZ235, a dual PI3K/mTOR inhibitor, reduced phosphorylation levels of the AKT targets p-FOXO and p-S6 and effectively induced apoptosis the Y79 and Weri-1 human retinoblastoma cell lines and in vivo in our retinoblastoma mouse model." (PMID 28445155, 2017). "In this study, we investigated whether there were anticancer activities of isoflavones in human retinoblastoma Y79 cells or not, and then we primarily studied its effects on the mTOR pathway in vitro and vivo." (PMID 29179444, 2017). "Indeed, in our study metformin activated the AMPK pathway in retinoblastoma cell lines at mM levels, as indicated by ACC phosphorylation and decreased phosphorylation of ribosomal protein S6 (a downstream effector of mTOR) and 4E-BP1 (a downstream effector of S6K)." (PMID 25215935, 2014).
chronic kidney disease (29 papers, 2012 to 2025). Impairment of the renal function secondary to chronic kidney damage persisting for three or more months. "Age and presence of three or more comorbidities in addition to chronic kidney disease were also risk factors associated with increased risk of death, whereas the use of mTOR inhibitor and the increasing baseline glomerular filtration rate were associated with decreased risk of death." (PMID 35185380, 2022). "The use of mTOR inhibitors has been found to ameliorate chronic renal failure, whereas overactivation of mTOR can lead to proteinuria, neutrophil damage, and renal tubular cell injury, which can affect renal function." (PMID 40141229, 2025). "Aminophylline has also been reported to reduce the elevated phospho-S2448 mTOR in an in vivo rat model of chronic renal failure." (PMID 39885115, 2025). "Aminophylline suppresses chronic renal failure progression by modulating the SIRT1/AMPK/mTOR-mediated autophagy process." (PMID 38808395, 2024). "mTOR pathway-activated autophagy protects podocytes from apoptosis, foot process effacement, and the progression of chronic kidney disease." (PMID 36766754, 2023). "Proteinuria and end-stage renal disease occurred in 3–5 weeks in podocyte-specific mTOR knockout mice." (PMID 36766754, 2023). "The autophagy activated by mTOR pathway protects podocytes from apoptosis, foot process effacement, and chronic kidney diseases progression." (PMID 30654583, 2019). "In podocyte-specific mTor knockout mice, the proteinuria and end-stage renal diseases (ESRD) occur in 3–5 weeks." (PMID 30654583, 2019). "ULK1 and ATG3 are autophagy associated genes wherein the components of the process are well deciphered in chronic kidney disease by affecting the mTOR pathway." (PMID 28349958, 2017). "Since these experimental studies represent the vast majority of human chronic kidney disease, their findings together imply that mTOR signaling acts as a rather common key pathway in the progression of renal disease." (PMID 22685654, 2012). "This study supports that mTOR can be a possible new target to attenuate the progression of chronic kidney disease." (PMID 22427849, 2012). "The studies in anti-thy1 acute and chronic renal disease unanimously indicate that unaffected mTOR signaling is critical for the very early and marked mesangial cell proliferation and subsequent normal glomerular repair of acute anti-thy1 glomerulonephritis." (PMID 22685654, 2012). "Together, these results suggest that quercetin inhibits fibroblast activation and kidney fibrosis involving a combined inhibition of mTOR and β-catenin signaling transduction, which may act as a therapeutic candidate for patients with chronic kidney diseases." (PMID 27052477, 2016). "The importance of mTOR signalling for podocyte survival has also been demonstrated in the setting of chronic kidney disease (CKD)." (PMID 35290515, 2022). "Furthermore, these studies suggest that inhibition of mTOR might be a novel, generally effective therapeutic approach to chronic kidney disease." (PMID 22685654, 2012). "mTOR can be a new target to attenuate the progression of chronic kidney disease even in those nephropathies of non-immunologic origin." (PMID 22427849, 2012). "It is worth noting that the ratio of phosphorylated-AKT to total AKT was found to be elevated in individuals with chronic kidney disease (CKD), with no significant impact on the phosphorylation of FOXO3 or mTOR." (PMID 38074330, 2023). "Therefore, it can be inferred that the molecular processes responsible for the development of left ventricular hypertrophy (LVH) in chronic kidney disease (CKD) are not influenced by FOXO3, ERK1/2, AMPK, and AKT/mTOR-mediated pathways." (PMID 38074330, 2023).
dilated cardiomyopathy (29 papers, 2014 to 2025). Cardiomyopathy which is characterized by dilation and contractile dysfunction of the left and right ventricles. "Variants in this gene have been described as causing electrolyte-losing tubulopathy and dilated cardiomyopathy due to the activation of mTOR signaling, suggesting a crucial role for Rag GTPase D in renal electrolyte regulation and cardiac function." (PMID 38790019, 2024). "Increased phosphorylation of mTOR Ser2448 has been observed specifically in the skeletal muscle of lamin-A deficient mice, which are characterized by skeletal muscle dystrophy and dilated cardiomyopathy." (PMID 33243288, 2020). "Cardiac-specific ablation of mTOR led to dilated cardiomyopathy and early mortality, thereby indicating the critical roles of mTOR activity for myocardial growth and proliferation during embryonic and early postnatal stages." (PMID 37274127, 2023). "Several studies have shown that mTOR is not only a pivotal inhibitor of autophagy, but also a key stimulator of dilated cardiomyopathy." (PMID 29290979, 2017). "Conventional ablation of mTOR in mice results in embryonic death while cardiac-specific mTOR knockout mouse also shows fatal, dilated cardiomyopathy." (PMID 28298952, 2017). "Inducible ablation of mTOR in adult cardiomyocytes (by tamoxifen induction of adult α-MHC-MerCreMer/Mtorfl/fl mice) also led to fatal dilated cardiomyopathy, thus suggesting the functional significance of mTOR in the maintenance of cardiac physiology and homeostasis." (PMID 37274127, 2023). "Furthermore, mTOR ablation in adult mouse myocardium also led to fatal dilated cardiomyopathy, indicating the role of mTOR in maintaining cardiac physiology and homeostasis." (PMID 33513917, 2021). "We provided evidence for that QSYQ could inhibit excessive myocardial autophagy by regulating the PI3K/Akt‐mTOR pathway and can be a potential therapeutic approach in treating the cardiovascular diseases such as myocarditis and dilated cardiomyopathy." (PMID 32881330, 2020). "It has been also documented that the activation of the PI3K/Akt‐mTOR pathway could inhibit myocardial fibrosis, hypertrophic or dilated cardiomyopathy by blocking myocardial fibrosis and then improving diastolic function." (PMID 32881330, 2020). "In contrast, genomic deletion of mTOR in the adult mouse myocardium resulted in a fatal, dilated cardiomyopathy characterized by apoptosis, autophagy, altered mitochondrial structure, and accumulation of eukaryotic translation initiation factor 4E-binding protein 1 (4E-BP1)." (PMID 25880554, 2015). "The proteins involved in the TGF-beta signaling pathway, mTOR signaling pathway, Rap1 signaling pathway, carbon metabolism, calcium signaling pathway, insulin signaling pathway, and dilated cardiomyopathy pathway may be related to the muscle growth and development of Jersey-yak." (PMID 38338049, 2024). "Namely, DEL are involved in the regulation of dilated cardiomyopathy (DCM), hypertrophic cardiomyopathy (HCM), insulin signaling pathway, and mTOR signaling pathway." (PMID 34880964, 2021). "In summary, the QSYQ compound could inhibit excessive myocardial autophagy by regulating the PI3K/Akt‐mTOR pathway to exert an effect on reparative myocardial fibrosis and can be a potential therapeutic approach to treat the cardiovascular diseases such as myocarditis and dilated cardiomyopathy." (PMID 32881330, 2020).
polycystic ovary syndrome (29 papers, 2012 to 2026). A disorder that manifests as multiple cysts on the ovaries. "In a study of rhesus macaques, testosterone treatment before menarche (to recapitulate hyperandrogenemia that characterizes PCOS) was associated with increased placental mTOR signaling during pregnancy." (PMID 34828683, 2021). "Notably, dysregulation of the mTOR pathway has been linked to gynecological disorders such as polycystic ovary syndrome (PCOS), premature ovarian failure (POF), and endometriosis." (PMID 40558485, 2025). "Recent study has shown that mTOR signaling cascade suppresses granulosa cell autophagy, and abnormalities in this process may cause reproductive diseases such as premature ovarian failure and polycystic ovary syndrome." (PMID 32265693, 2020). "In conclusion, continuous light exposure disrupts ovarian function by altering the leucine-mTOR-autophagy axis in granulosa cells, thus leading to polycystic ovary-like phenotypes and elevated AMH levels." (PMID 41362744, 2026). "This study investigates the role of the c-Fos/estrogen receptors (ERs)/mTOR pathway in lipid metabolism in human follicular granulosa cells of individuals with polycystic ovary syndrome (PCOS)." (PMID 40937413, 2025). "The PI3K/Akt/mTOR signaling pathway was involved in cellular autophagy in chicken hepatocytes and rat granulosa cells with polycystic ovary syndrome, respectively." (PMID 38790208, 2024). "Melatonin has been associated with increased expression of members of the PI3K/Akt/mTOR pathway and suppressed autophagy and apoptosis in polycystic ovary syndrome." (PMID 36559263, 2022). "For instance, it is also approved for the treatment of polycystic ovary syndrome, and its regulatory action on the mammalian target of rapamycin (mTOR) signaling pathway implies an interesting potential as an anti-cancer agent." (PMID 31801292, 2019). "Besides its inhibition of mTOR, metformin decreases basal and insulin-stimulated aromatase expression, which is an important mechanism of its usefulness in polycystic ovary syndrome." (PMID 29137418, 2017). "PK1 also promotes polycystic ovary syndrome (PCOS) pathogenesis via the PI3K/AKT/mTOR pathway, making miR-28-5p a potential therapeutic target for this pathology." (PMID 35207461, 2022). "The mTOR signaling pathway is significantly downregulated in the oocytes of patients with polycystic ovary syndrome (PCOS)." (PMID 36396932, 2022). "Previous studies have demonstrated that metformin can increase the expression of SIRT3 and GPX4, significantly elevate the levels of p-mTOR and p-AMPK, and improve polycystic ovary syndrome in mice by inhibiting ovarian ferroptosis." (PMID 41480421, 2025). "In polycystic ovary syndrome (PCOS) rat models, ST inhibited autophagy and inflammation by inhibiting the PI3K/AKT/mTOR and TLR4/NF-κB pathways, respectively." (PMID 38131990, 2023). "As such, placental mTOR signaling can be altered in response to several environmental and pregnancy-related factors including maternal obesity, nutrient restriction, gestational diabetes mellitus (GDM), preeclampsia (PE), polycystic ovarian syndrome (PCOS) and maternal smoking." (PMID 34828683, 2021).